MET (MET proto-oncogene, receptor tyrosine kinase)
Diseases named in the same sentence as MET in open-access papers (continued):
Sharing a sentence is not in itself a finding about the gene and the disease.
lung cancer (continued). "MMAE-conjugated VBC101-F11 displayed superior TGI over ABBV-399 in lung cancer cell line xenografts (3 mg/kg), and conjugation to a novel, undisclosed DNA replication inhibitor resulted in similar efficacy to AZD9592 in EGFR-low/c-MET-high and EGFR-/c-MET-moderate models." (PMID 39065587, 2024). "Furthermore, IAG933 plus the MET inhibitor capmatinib induced profound tumor shrinkage in the EBC-1 MET-amplified CDX model of lung cancer, while no activity was seen for IAG933 alone." (PMID 38565920, 2024). "In this scenario, customized medicine has brought successful outcomes in drug selection for lung cancer patients with NSCLC based on the paradigms of their molecular profiles, specifically those with positive genetic alterations in EGFR, ALK, ROS-1, HER2, BRAF, MET, and RET genes." (PMID 39410578, 2024). "However, MET fusions are rarely detected in lung cancer, and their sensitivity to therapeutics has not been systematically analyzed." (PMID 36829199, 2023). "A positive correlation between the expression of HER3 and MET was noted in 24 human colon cancer cell lines (r = 0.54), but not in 25 breast and 22 lung cancer cell lines (r = 0.01 in breast cancers, and r = 0.27 in lung cancers) (data not shown)." (PMID 36751113, 2023). "Variant-specific PCR was performed for 744 tumors with a normal 5′/3′-end expression ratio: there were no rearrangements in 172 EGFR/ALK/ROS1/RET/MET-negative lung cancers and 125 pediatric tumors, while NTRK3 fusions were detected in 2/447 (0.5%) non-lung adult malignancies." (PMID 37762506, 2023). "Further, in vitro studies showed that ARQ affects cell proliferation in cells not expressing MET and does not inhibit MET phosphorylation in lung cancer cells with low basal levels of MET expression or in gastric carcinoma cells characterized by MET amplification and constitutive MET activation." (PMID 35574376, 2022). "Two patients (P003 and P006) who met Amsterdam criteria, whose families suffered from colorectal cancer, lung cancer and bladder cancer, were not identified as MMR mutation carriers, but they carried many other tumor-associated genes, such as BRCA2, CDH1, MET, ATM, NF1." (PMID 35372080, 2022). "PD-L1-enhancing oncogenes, such as EGFR, ALK, MET, AKT, MYC, and CDK5, were not identified as hits in this study because KRAS mutations in lung cancer cell lines (H2009 and H460) could establish distinct PD-L1 regulatory axes." (PMID 36357569, 2022). "Hence, our observations of MET dependence in EGFR-mutant lung cancers are unlikely to be an experimental artifact." (PMID 34516823, 2021). "Indeed, the MET pathway was shown to be upregulated in KRAS-mutant lung cancer after MAPK inhibition and after treatment with KRAS inhibitors, an effect that could be enhanced by mutant MET." (PMID 34684076, 2021). "For example, lung cancer tissue samples expressed reduced lncRNA MIR22HG levels compared with normal lung tissues, and MIR22HG could accelerate lung cancer cell survival and cell death signaling by regulating the oncogenes YBX1, MET, and p21." (PMID 37304650, 2021). "Specifically, lung cancer patients with MET exon 14 skipping are responsive to MET inhibitors despite not having other activating alterations, while melanoma patients expressing a BRAF isoform lacking exons 4–8, which encodes for the RAS binding domain, exhibit resistance to BRAF inhibitors." (PMID 33482911, 2021). "Therefore, we can conclude that in lung cancer cells, Grb2, SCOS and PKCμ are the potential target molecules for SIPA1, thus promoting the recycling of MET, in order to maintain the MET receptor at a high level, thereby enabling the transmission of the HGF signal within the cells." (PMID 33917539, 2021).
lung cancer (continued). "Other genetic tests that can be performed and are not part of the routine molecular diagnostics of lung cancer include the MET gene amplification test, especially in patients with progression during EGFR TKI therapy in the absence of the Thr790Met resistance mutation in exon 20 of the EGFR gene." (PMID 34945842, 2021). "Studies have shown that in lung cancer, after aberrant splicing, the expression of BCL2L1, MDM2, MDM4, NUMB, and MET may play an important role in tumorigenesis, which may be due to the effects on cell apoptosis, cell proliferation, and intercellular cohesion‐related pathways." (PMID 33047900, 2020). "A lung cancer with c-MET amplification also demonstrated high sensitivity to crizotinib, a tyrosine kinase inhibitor targeting the anaplastic lymphoma kinase gene (ALK), suggesting cancers with increased c-MET levels may be sensitive to ALK inhibitors." (PMID 29416799, 2018). "Potentiation of EGFR action by MET in lung cancer has been found to be independent of HGF leading to speculation in favor of an intracellular lateral signaling cascade." (PMID 29348142, 2018). "Hence, in the current study, we sought to not only determine if MET is a target for CBL-mediated degradation and ubiquitination in NSCLC, and also whether it could serve as a novel therapeutic target in lung cancer." (PMID 28835699, 2017). "However, some lung cancer cells with amplified MET and overexpressed EGFR fail to respond to combined treatment with EGFR and MET inhibitors or develop resistance to dual EGFR/MET inhibition." (PMID 28968967, 2017). "As previous studies suggested that the inhibition of ALK and IGF1R pathways may potentiate chemotherapy and radiotherapy in lung cancer, crizotinib might be an effective additional therapeutic agent in patients with aggressive ARMS tumours that overexpress ALK, MET and IGF1R proteins." (PMID 26445453, 2015). "Second, miR-206 can directly regulate mRNA expression by targeting the 3′-UTR of MET and BCL2, and inhibit protein expression of cyclin D1 and gene expression of cyclin D1, cyclin D2 and matrix metalloproteinase 9 (MMP-9), while increased p57 gene expression in lung cancer cell (A549)." (PMID 26325180, 2015). "The authors also reported on 6 NRAS mutant lung carcinoma cell lines and their sensitivity to the MEK inhibitors selumetinib and trametinib and their resistance to erlotinib (EGFR-TK inhibitor), crizotinib (ALK/MET/RON/ROS1 inhibitor) and linsitinib (IGF-1R inhibitor)." (PMID 25277205, 2014). "Co-activation of MET, AXL, ERBB2, and EPHA2, and co-activation of DDR1 with EGFR, DDR2, HCK, PDGFRA, and FGR is evidence that simultaneous activation of multiple tyrosine kinases may be common in lung cancer." (PMID 23300999, 2013). "Indeed, MET and EGFR are both negatively correlated with survival in patients with lung cancer." (PMID 23844053, 2013). "In addition, ALK/MET inhibitor crizotinib also inhibited growth of HCC78- and ROS1-positive tumors suggesting that lung cancer patients with ROS1 rearrangement could benefit from targeted therapy using crizotinib." (PMID 22928112, 2012). "METex14-altered lung cancer has been identified in patients expressing PD-L1 (n = 147; PD-L1 expression, 0%, 1–49%, and 50% accounting for 37%, 22%, and 41%, respectively, across 111 evaluable tumor samples); however, neither interaction nor complex formation was detected between c-MET and PD-L1." (PMID 35884507, 2022). "The results of this study suggest that combined use of EGFR-TKI and MET inhibitors or inhibition of downstream signaling molecules, such as PI3K or MEK, might be a better second or third-line strategy for a group of patients with advanced lung cancer harboring wild-type EGFR." (PMID 26919104, 2016).
lung cancer (continued). "However, in other tumor types such as lung cancer and gastric cancer, MET gene amplification, without Chromosome 7 gain, was found to be a potent activator of MET pathway signaling, underscoring the complexity of MET pathway activation as an oncogenic driver across different tumor types." (PMID 26636767, 2015). "As opposed to MET alterations, ALK fusions represent a well-established therapeutic target in lung cancer, as they are detected in 3–7% of NSCLCs and have been associated with an absence of smoking, younger age, and adenocarcinoma histology." (PMID 35012520, 2022). "No recurrent MET fusions were identified, some of the fusion partners included HLA-DRB1-MET (lung cancer), CD47 (lung cancer), CAPZA2 (gastric cancer), AKAP9 (hepatobiliary cancer), CLIP2 (hepatobiliary cancer), and SLC25A19 (ovarian cancer)." (PMID 36369474, 2022). "At present, the potential effects of MET and/or AXL targeting have been reported in renal cell carcinoma, lung cancer, and triple‐negative breast cancer." (PMID 34766112, 2020). "AXL hyperactivation and evidence for EMT were previously reported in multiple in vitro and in vivo EGFR-mutant lung cancer models with acquired resistance to erlotinib independent of the EGFR T790M alteration and MET activation." (PMID 31815659, 2019). "In our previous studies in lung cancer, the results not only showed the interation of c-CBL and MET but also showed knockdown c-CBL induced MET overexpression and became sensitive to MET inhibitors (data not shown)." (PMID 27244893, 2017). "“Non-KRAS oncogene-driven lung cancer subtypes (e.g., ROS1, MET, BRAF, HER2, RET) is less well-studied, however, most of these other non-KRAS molecular subtypes (possibly apart from BRAF V600 mutation and MET gene alteration) are associated with a light-to-never smoking history." (PMID 34575691, 2021). "Whereas MET-amplified lung cancer cells do not respond to EGFR inhibition, their growth is strongly inhibited by MET tyrosine kinase inhibitors, confirming that these cells are addicted to MET signaling." (PMID 28968967, 2017). "While EGFR-PYK2 co-targeting was identified to be synergistic in TNBC, PYK2 may have a larger role in coordinating EGFR and c-MET signalling depending on the cancer types, evident by data showing PYK2 activation was not affected by Gefitinib in lung cancer cells." (PMID 29920512, 2018).
breast carcinoma (456 papers, 2004 to 2026). "The results provide valuable insights into the molecular mechanisms underlying the effects of TAS-115 on breast cancer progression, particularly in terms of apoptosis, cell survival, and the c-MET/HGF signaling axis." (PMID 41289612, 2025). "Previous data demonstrated that the overexpression of MET induced resistance to endocrine drug fulvestrant in breast cancer cell lines, an effect that was further associated with increased cancer cell migration and invasion." (PMID 39742369, 2024). "A meta-analysis of 6010 breast cancer cases indicated the association between MET overexpression and poor relapse-free survival in hormone receptor-positive disease." (PMID 39742369, 2024). "MET is expressed in different molecular subtypes of breast cancer and is associated with aggressive phenotypes." (PMID 39742369, 2024). "The hepatocyte growth factor receptor MET is aberrantly expressed in breast cancer and is associated with poor prognosis." (PMID 37173782, 2023). "Within this group, only four recommendations were of tier 1 clinical evidence level (1x PIK3CA/KRAS-mutated breast cancer, 1x MET-mutated kidney cancer, 1x ALK fusion-positive NSCLC, and 1x BRCA2-mutated pancreas cancer)." (PMID 38136436, 2023). "To determine the associations between CCR2 and MET expression, we analyzed mRNA and protein levels in breast cancer." (PMID 35405500, 2022). "Overexpression of MET was associated with basal-like breast cancer in humans, while in a murine model mutationally activated Met induced diverse mammary adenocarcinomas." (PMID 35163327, 2022). "Promoter in gastric cancer in association with α3 integrins.Promoter in breast cancer in association with integrins promoting a signaling pathway (HGF/c-MET).Promoter in liver cancer by increasing Rac/Cdc42 activity." (PMID 34830819, 2021). "We found that TIC/EMT-enriched breast cancers were elevated in gene signatures associated with both MET and FGFR1 signalling pathway activation." (PMID 33772015, 2021). "Activating point mutations of MET and MET amplification have been reported in several cancer types, including gastric cancer, breast cancer, hepatocellular carcinoma, and non-small cell lung cancer." (PMID 33596979, 2021). "Elevated levels of MET protein are detected in 15–20% of all breast cancers and are associated with poor outcome across subtypes and within the TNBC subclass itself." (PMID 33772015, 2021). "MET overexpression in breast cancer-associated adipose tissue composed of mesenchymal stem cells has also been correlated with recurrence and a potential role in tumorigenesis." (PMID 33437521, 2020). "The MET pathway is associated with breast cancer progression and anti-Met therapies are currently evaluated in breast cancer patients." (PMID 27894094, 2017). "Elevated level of c-Met RNA, protein and a MET transcriptional profile is linked with the mammary tumor progression and c-Met mediated MAPK cascade activation." (PMID 28415766, 2017). "MET overexpression has been associated with an invasive phenotype during breast cancer progression in vivo and in animal models." (PMID 27055285, 2016). "Because MET expression is increased in the triple-negative subset of breast cancer and is associated with worse prognosis, targeting MET signaling in this population is a rational therapeutic strategy." (PMID 26123926, 2015). "To determine if MET-T1010I alters breast cancer pathophysiology, we compared its effects to MET-WT representing MET overexpression in breast cancer and to MET-Y1253D tyrosine kinase domain mutation representing an activated MET receptor." (PMID 25605252, 2015).
breast carcinoma (continued). "The prognosis of other cancer types such as non-small cell lung cancer, colorectal cancer, ovarian cancer, breast cancer were also reported associated with the high levels of MET and/or HGF expression." (PMID 24416238, 2014). "We recently performed chemosensitivity assays in the BRCA-deficient human breast cancer cell line HCC1937 in order to further assess the specific antiproliferative potential of MET relevant to BRCA1 deficiency." (PMID 26097796, 2012). "High c-MET expression in glioblastoma, breast cancer, gastric cancer, and ovarian cancer is associated with poor survival." (PMID 21283737, 2011). "In addition, MET amplification and mutation were detected in 4.7% and 9% of advanced breast cancer patients, respectively." (PMID 39742369, 2024). "As MET is overexpressed in breast cancer (20%–30%), and METamp and MET overexpressions are associated with anti-EGFR resistance in NSCLC, it was hypothesized that MET contributes to anti-EGFR resistance in TNBC." (PMID 36999986, 2023). "Importantly, basal breast cancers that display elevated MET and FGFR1 signatures are associated with poor relapse-free survival." (PMID 33772015, 2021). "In addition, a meta-analysis indicated that c-MET overexpression was associated with overall and disease-free survival in breast cancer patients." (PMID 34344422, 2021). "Moreover, overexpression of CXCR4, HGF, and c-MET in primary breast cancer is associated with worse patient outcomes in females." (PMID 32188473, 2020). "The HGF growth factor receptor MET is potentially functionally altered due to an uncommon germline single nucleotide polymorphism (SNP), MET-T1010I, in many cancer lineages including breast cancer where the MET-T1010I SNP is present in 2% of patients with metastatic breast cancer." (PMID 25605252, 2015). "EGFR/MET complex associated with SRC were reported in EGFR TKI-resistant breast cancer cells." (PMID 24714091, 2014). "In breast cancer cells, MET and SRC cooperate to compensate for the loss of EGFR TKI activity." (PMID 24714091, 2014). "In a study that evaluated hepatocyte growth factor (HGF) and the high affinity hepatocyte growth factor receptor (MET) in 59 women with breast cancer related LE, mutations leading to truncation or missense changes in evolutionarily conserved residues of HGF and MET were identified." (PMID 23613720, 2013). "Importantly, expression of p-Y907 PARP1 is positively associated with expression of c-MET in the tumor tissues of breast cancer patients, and combination of c-MET and PARPi synergistically suppresses the growth of xenograft tumors which have high c-MET and p-Y907 PARP expression." (PMID 36284291, 2022). "However, few studies have assessed the frequency of MET mutations in primary breast cancer." (PMID 25887320, 2015). "Amplification of MET may also be important in other molecular subtypes of breast cancer: in a study of 130 Her2-positive breast cancers, both MET and HGF amplification were associated with trastuzumab failure and patients with MET amplified tumours had a shorter time to progression." (PMID 25887320, 2015). "Such a redundant signaling via amplified MET may participate in breast cancer malignant behaviors during the treatment with anti-Her-2 antibody, Trastuzumab (Herceptin®), possibly due to association (and re-activation) of Her2 with amplified MET." (PMID 23296269, 2013). "Mechanistically, TAS-115 downregulated c-MET and its downstream mTOR signaling, indicating a targeted disruption of survival and growth pathways in metastatic breast cancer cells." (PMID 41289612, 2025). "This is supported by the fact that anti-MET mAbs were able to impact 3 different breast cancer cell lines." (PMID 40401526, 2025).